MIR335 (microRNA 335)
Synonyms: hsa-mir-335; MIRN335; miRNA335; mir-335
Gene: MicroRNA gene on chromosome 7 (130,496,111 to 130,496,204, forward strand). Ensembl gene ENSG00000199043.
Gene Ontology:
Biological process: miRNA-mediated post-transcriptional gene silencing
Cellular component: RISC complex
Homologues: Orthologues: chimpanzee ptr-mir-335 (100% identical), guinea pig MIR335 (97% identical), macaque MIR335 (97% identical), pig MIR335 (95% identical), rat rno-mir-335 (94% identical), mouse Mir335 (90% identical), dog MIR335 (89% identical), rabbit MIR335 (62% identical).
Diseases named in the same sentence as MIR335 in open-access papers:
MIR335 is named in the same sentence as 6 diseases in open-access papers, as found by Europe PMC text mining. Sharing a sentence is not in itself a finding about the gene and the disease. The quoted sentences say what the papers report.
asbestosis (1 paper, 2023). A lung disorder caused by inhalation of asbestos fibers. "In our study, carriers of two polymorphic MIR335 rs3807348 alleles were more likely to develop MM compared to subjects with asbestosis, even after adjustment for age." (PMID 38038422, 2023). "Compared to subjects with asbestosis, carriers of two polymorphic MIR335 rs3807348 alleles were more likely to develop MM (OR = 1.82, 95% CI = 1.05–3.16, P = 0.033), even after adjustment for age (OR = 0.35, 95% CI = 1.10–3.50, P = 0.022)." (PMID 38038422, 2023).
gastric cancer (1 paper, 2020). A primary or metastatic malignant neoplasm involving the stomach. "It is known that MIR335 negatively regulates the metastasis in gastric cancer by targeting BCL2L2 and SP1." (PMID 32582296, 2020).
neuroblastoma (1 paper, 2020). Neuroblastoma (NB) is the most common solid, extracranial childhood tumor. "In addition, MIR335 inhibits the mRNA transcribed by LRG1 gene reducing the migration of neuroblastoma cells." (PMID 32582296, 2020). "In neuroblastoma cells, MIR335 downregulates the ROCK1 and MAPK1 genes, involved in the non-canonical TGF-β pathways." (PMID 32582296, 2020).
cancer (1 paper, 2020). A tumor composed of atypical neoplastic, often pleomorphic cells that invade other tissues. "MIR335, present in our EVs, also appears to play the role of proto-oncogene suppressor in a wide variety of cancers." (PMID 32582296, 2020). "In this way, MIR335 contributing to the progression of cancer." (PMID 32582296, 2020).
tumor (1 paper, 2025). "Mir335 targets CRKL, thereby inhibiting the migration, invasion, and proliferation of tumor cells, arresting the cell cycle at the G0/G1 phase, and promoting apoptosis in GC cells." (PMID 40150719, 2025).
MIR335 also shares sentences with these, for which no sentence is quoted: breast carcinoma (1 paper).